CCDC200 (coiled-coil domain containing 200)
Synonyms: LINC00854; TMEM106A-AS1; TMEM106AAS1
Gene: Protein-coding gene on chromosome 17 (43,216,941 to 43,305,397, reverse strand). Ensembl gene ENSG00000236383.
Homologues: Orthologues: chimpanzee CCDC200 (95% identical), macaque CCDC200 (92% identical), rat Ccdc200 (41% identical), mouse Ccdc200 (40% identical).
Diseases named in the same sentence as CCDC200 in open-access papers:
CCDC200 is named in the same sentence as 3 diseases in open-access papers, as found by Europe PMC text mining. Sharing a sentence is not in itself a finding about the gene and the disease. The quoted sentences say what the papers report.
Infertility (1 paper, 2024). "In line with this, we found that numerous infertility-related DMR-associated genes are expressed during spermatogenesis (e.g., VPS37D, FAM9B [MIM: 300478], SLCO3A1, and CCDC200)." (PMID 38759652, 2024).
CCDC200 also shares sentences with these, for which no sentence is quoted: leukemia (1 paper); tumor (1).